CD4 (CD4 molecule)
Diseases named in the same sentence as CD4 in open-access papers (continued):
Sharing a sentence is not in itself a finding about the gene and the disease.
tumor (continued). "However, CTLs are not activated by direct recognition of the antigens expressed by tumor cells; they need help from dendritic cells (DCs) and CD4+ helper T cells." (PMID 21253521, 2010). "Notably, significant infiltrations of CD8+ and CD4+ T cells were detected in the tumour tissues of these C57BL/6 mice treated with TGFalphaL3SEAD227A, suggesting the involvement of T cells in this tumour-inhibitory process." (PMID 21176167, 2010). "Furthermore, recent studies demonstrate that adoptively transferred CD4+ T cells can induce tumor rejection also independently of CD8+ T cells." (PMID 21152437, 2010). "To investigate whether TGFαL3SEAD227A inhibited tumour growth in a similar way, we examined for infiltration of CD4+ and CD8+ T cells in fusion protein-treated tumour tissue." (PMID 21176167, 2010). "We extended previous finding by demonstrating that the CpG-ODNs could enhance the antitumor efficacy of adoptive transferred TILs, which was correlated to enhanced activity and proliferation of tumor infiltrating CD4+ T cells and CD8+ T cells." (PMID 20981279, 2010). "This is in accordance with data showing that natural CD4+CD25+ Tregs may play a critical role in the progression of a number of cancers by suppressing anti tumor immune response effects." (PMID 20205946, 2010). "Overall, these results suggest that effective tumor suppression of post-GC B cells may depend on specific signals delivered by CD4+ T cells." (PMID 21179576, 2010). "Some studies have demonstrated that chronic activation of B-cells contributes to tumor development by inhibiting the activity of CD4+ T-cells by yet unknown mechanisms." (PMID 20525350, 2010). "It is possible that these CD4+ T-cells may synthesize pro-inflammatory cytokines related to the protective anti-tumor immune response." (PMID 20525350, 2010). "The majority of the studies used mRNA transfected in dendritic cells and were focused on the stimulation of CD8+ cytotoxic T lymphocyte response, as well as on the induction of CD4+ T helper cell response, in order to obtain optimal and sustained immune responses capable of eliminating tumor cells." (PMID 20961459, 2010). "Taken together, endogenous IL-23 expression promotes tumor incidence and growth, while application of IL-23 at the excessive amount induces antitumor immune responses with the characteristics immune responses mediated by the function of CD4+ and CD8+ T cells." (PMID 20885915, 2010). "Additionally, we identify a small population of CD8- but TIA-1+ tumor infiltrating cells representing populations of TCRγδ cells and neutrophils and to a lesser extent CD4+ T cells, macrophages, NK cells, and NK/T cells." (PMID 21179245, 2010). "It is not clear whether intratumoral Treg cells represent Treg cells pre-existing in healthy mice, or arise from tumor-specific effector CD4+ T cells and thus representing adaptive Treg cells." (PMID 21049016, 2010). "Moreover, GITRL expression on tumor cells enhanced proliferation and reduced the numbers of apoptotic CD4+ and CD8+ T cells in vitro." (PMID 20936139, 2010). "This resulted in enhanced tumor infiltration by CD4+ and CD8+ T cells." (PMID 20936139, 2010). "This may explain why some animals survived, despite the high number of tumor infiltrating CD4+ T-cells." (PMID 20525350, 2010). "Tumor-specific CD4+ T cells regulate the survival and persistence of CTLs as memory cells." (PMID 21048993, 2010). "Thus, tumor antigen-specific CD4+ T cells essentially contribute to anti-tumor immunity which has strongly stimulated the interest in the identification of their target epitopes." (PMID 21152437, 2010). "Indeed, suppression in the tumor microenvironment is mediated by a unique subset of CD4+CD25highFoxp3+ Tregs that produce IL-10 and TGF-β, exerting a more suppressive effect on proliferation." (PMID 21437225, 2010). "Importantly, the HCV TCR-transduced CD4+ T cells secreted significant amounts of cytokine when stimulated with HCV+ tumor cells." (PMID 20686664, 2010).
tumor (continued). "In addition, CD4+ T cells provide help for the maintenance and expansion of CTLs by secreting cytokines such as interleukin (IL)-2 and can eradicate tumor cells directly." (PMID 21076523, 2010). "Indeed, we demonstrated that adoptively transferred CD4+ T cells, through CD40L-CD40 interactions, license tumor-associated DCs to prime endogenous antitumor CD8+ T cells." (PMID 21076522, 2010). "Interestingly, tumor samples from ECDα2 boosted mice shown smaller number of the ratio of Foxp3+/CD4+ (12%) compared with that of control mice (30%, P < 0.001)." (PMID 21067607, 2010). "Constitutively active Stat-5A (Stat-5A1*6) over-expression efficiently elevates Bcl-2 levels in CD4+ T cells and protects them from tumor-induced death while dominant-negative Stat-5A over-expression fails to do so, indicating the importance of Stat-5A-signaling in CD4+ T cell survival." (PMID 19812686, 2009). "Receptor expression in CD4+ T cells could be efficiently restored back to normal level by theaflavin-treatment of tumor cells." (PMID 19812686, 2009). "The direct CD4+ T cell response to the allogeneic MHC class II antigens on allogeneic DCs will provide potent T cell help for the generation of antigen-specific CD8+ CTL responses to autologous tumor peptides presented by the shared MHC class I molecules." (PMID 20182533, 2009). "Understanding the mechanisms of tumor-induced CD4+ T cell apoptosis as well as its amelioration by any biological response modifier is, therefore, of high importance from the point of view of amelioration of tumor-induced immuno-suppression." (PMID 19812686, 2009). "Finally, to re-confirm the role of tumor-shed PGE2 in materialising the CD4+ T cell killing effect of tumor, we undertook two approaches." (PMID 19812686, 2009). "We observed CD4+ lymphocyte tumor infiltrations were detected in all mice groups." (PMID 19178753, 2009). "After confirming the Stat-5-mediated pathway as the major pathway in tumor-induced CD4+ T cell apoptosis, we undertook two different approaches to identify the isoform(s) of Stat-5 involved since both Stat-5A and Stat-5B isoforms play critical role in Bcl-2 induction in T cells." (PMID 19812686, 2009). "Since both APCs and tumors naturally process and present these tumor-associated peptides to both CD8+ and CD4+ T cells, they could be used in devising new immunotherapeutics against metastatic melanoma." (PMID 20016802, 2009). "Therefore, CD4-based treatment in vaccine strategy should be investigated further for developing more effective anti-tumor immunotherapy." (PMID 19707583, 2009). "Inability of externally added IL2 to overcome tumor-PGE2 effect indicated that IL2 deprivation is not the primary cause of CD4+ cell death in our system." (PMID 19812686, 2009). "First, on the anti-tumor immunity: indeed, in human tumors a skew towards Th2 type of tumor-specific CD4+ T cells has been described in patients with advanced malignancies, while high levels of infiltrating Th1 cells in the tumors correlate with a better prognosis." (PMID 19798410, 2009). "In conclusion, our data provide direct evidence that tumor-derived Cox-2-dependent PGE2 affects IL2Rγc-driven signals in CD4+ T cells by down-regulating IL2Rγc and inactivating Jak resulting in impaired activation of downstream signals as shown by decreased phosphorylation of Stat." (PMID 19812686, 2009). "Although these results clearly implicate a tumor-protective effect of B7-H3, the exact physiologic/pathologic role of B7-H3 remains ambiguous, because B7-H3 has also been shown to inhibit CD4+ and CD8+ T cell proliferation and IFN-γ production mediated by anti-CD3 in mice." (PMID 20035626, 2009). "There was a modest increase in IFN-γ-secreting CD4+ T cells throughout the course of tumor growth." (PMID 19226468, 2009).
tumor (continued). "By culturing purified human peripheral CD4+ T cells or Jurkat cells with spent media of theaflavin- or celecoxib-pre-treated MCF-7 cells, we show that tumor-shed PGE2 severely impairs interleukin 2 receptor γc (IL2Rγc)-mediated survival signaling in CD4+ T cells." (PMID 19812686, 2009). "Moreover, it was shown that adoptive cell transfer of NY-ESO-1-reactive CD4+ T cells into melanoma patient resulted in a great inhibition of the growth of metastatic tumour tissue." (PMID 19277034, 2009). "Among the bacterial vectors, L. monocytogenes has emerged as a promising vector, because in animal models it is able to induce both CD8+ and CD4+ immune responses to elicited regression of established tumours, and to overcome central tolerance by expanding low avidity CD8+ T cells specific for E7." (PMID 19473517, 2009). "Considering the wide distribution of cyclin D1 in tumor cells, generation of specific CD4 CTLs, might add therapeutic activity in HLA-DR-expressing cancer cells." (PMID 19707583, 2009). "Moreover, it has recently been reported that DCs are capable of inducing conversion of naive CD4+ T cells to adaptive CD4+ CD25+ Foxp3+ Treg in the presence of TGF-β or IL-10 derived from tumor cells." (PMID 20182533, 2009). "CD4+ T cells, which recognize these tumor epitopes, could be activated and would then be able to recruit professional APCs as well as CTLs and NK T cells." (PMID 20016802, 2009). "Tumour-infiltrating lymphocytes (CD4, CD8, Foxp3), mast cells (MCs) (tryptase and chymase), microvessel count (MVC) and VEGF were determined by immunohistochemistry in two series of MPM patients: 60 patients treated with intra-pleural preoperative IL-2 and 33 patients untreated." (PMID 19935800, 2009). "The authors suggested that interactions between CD4 T cells and NK cells or macrophages may have contributed to the anti-tumor immunity of the CD4 T cells." (PMID 19707583, 2009). "The direct CD4+ T cell response to the semi-allogeneic MHC class II antigens on semi-allogeneic DCs will provide potent T cell help for the generation of antigen-specific CD4+ T cell response to autologous tumor peptides presented by the shared MHC class II molecules." (PMID 20182533, 2009). "All these results strongly reconfirm our hypothesis that Stat-5A protects CD4+ T cells from tumor-induced apoptosis and theaflavins utilize this isoform of Stat-5 to assert its protective effect." (PMID 19812686, 2009). "Therefore, fully activated tumour-specific CD4+ T cells are important for inducing an effective immunotherapy of the tumour-bearing hosts." (PMID 19277034, 2009). "All these data confirmed the role of Cox-2-derived PGE2 in tumor-induced CD4+ T cell killing." (PMID 19812686, 2009). "In this situation too, prior treatment of the tumor cells with theaflavins could bring back the phosphorylation status of Stat-5A to normal level in CD4+ T cells." (PMID 19812686, 2009). "Also, strong CD8+ and CD4+ T cell immune memory responses to the presentation of tumor antigens (Ags) seem to require processing and crosspresentation by professional antigen presenting cells (APCs)." (PMID 20016802, 2009). "Induction of anti-tumor immunity by CD4+ CD25+ Treg depletion was first proved in mouse models." (PMID 19175928, 2009). "Likewise, our strategy is that PBMCs are used as sources of CD4+ T-cell for generating tumour-specific Th cells." (PMID 19277034, 2009). "Recent advances in understanding of contribution of CD4+ in anti-tumor immunity, as well as some intriguing developments in the clinic, indicate that due to the cooperative role of CD4+ helper T cells for CD8+ cytotoxic T cells, they have the unrealized potential in tumor eradication." (PMID 19812686, 2009). "Cyclophosphamide depletes CD4+CD25+ Tregs in mice injected with tolerogenic syngeneic tumour cells." (PMID 19384299, 2009).
tumor (continued). "Above data also signify that normalization of this signaling pathway may be the mechanism by which theaflavins prevent tumor-induced caspase-3-dependent CD4+ T cell apoptosis." (PMID 19812686, 2009). "Recent evidence suggests that CD4+CD25+FoxP3+ regulatory T-cells (Treg) may be responsible for the failure of host anti-tumour immunity by suppressing cytotoxic T- cells." (PMID 19732435, 2009). "The impact of the CD4+CD25 T-regs in anti-tumor immunity has been widely reported in animal models." (PMID 19707583, 2009). "There is a need to carefully control the size of the CD4+CD25high regulatory T cell population in vivo to achieve a balance between the necessity to suppress auto-reactivity and the ability to allow appropriate responses to foreign and tumor antigens." (PMID 19046457, 2008). "Abundant accumulation of Tregs in tumor tissues might be due to the induction of CD4+CD25+ Tregs from peripheral CD4+CD25- T lymphocytes and/or migration of Tregs from other parts of the body to the tumor area by chemotactic factors like CCL22." (PMID 18294387, 2008). "Rather, the CD8/CD4 ratio and CD4/8 status appear to be critical factors in anti-tumour immunity." (PMID 18349839, 2008). "A similar dual activity has also been described in a Calendula extract, LACE, which produces an in vitro cytotoxic activity and in vivo immunomodulatory effect on tumour cell lines, including human and mouse melanioma cells, increasing the number and activation of CD4+, CD19+ and NKT cells." (PMID 18366723, 2008). "Interestingly, we observed a 3 fold decrease in the absolute percentage of CD4+ T cells and CD8a+ T cells infiltrating into the tumor after administration of PC61." (PMID 18431473, 2008). "The present study confirms the decrease in the CD4+/CD8+ ratio with increasing tumor burden." (PMID 17338814, 2007). "Loss of expression of HLA class II molecules on tumor cells affects the onset and modulation of the immune response through lack of activation of CD4+ T lymphocytes." (PMID 18425214, 2007). "Thus it is possible that local PDT treatment of tumours leads to release of factors capable of bypassing the need for CD4+ T cells in the activation of DCs." (PMID 17505510, 2007). "This in turn may facilitate development of the CD4+ T cell response, which as observed in the model described here, is capable of tumour rejection." (PMID 17294404, 2007). "CD4+CD25+ regulatory T cells (Treg) are known to influence T cell responses to tumours." (PMID 17294404, 2007). "SD rats with SCCs had decreased CD4+/CD8+ ratios, which were associated with a greater tumor load." (PMID 17338814, 2007). "Secretion of GM-CSF by genetically-modified tumor cells stimulates cytokine release at the vaccine site to activate antigen-presenting cells, which prime CD4+ and CD8+ T cells to recognize circulating tumor-associated antigens, thereby inducing a tumor-specific cellular immune response." (PMID 17868452, 2007). "Transfection of Neuro-2A cells with IL-2 and IL-12 abolished their tumorigenicity in syngeneic A/J mice, and when injected into established tumours provoked an antitumour immune response involving CD8+ and CD4+ T cells, which led in some cases to complete tumour eradication." (PMID 17595664, 2007). "This process usually depends on mhc class-ii restricted cd4+ T-cell help that provides the cytokine signals necessary for activation and clonal expansion of tumour reactive ctls and for memory formation that can then provide the much-desired long-term antitumour protection." (PMID 17576455, 2006). "Also, patients with invasive disease had lower tumour infiltration of CD4+ (P<0.05) and CD8+ T-lymphocytes (P<0.01) and had evidence of a systemic inflammatory response (P<0.05)." (PMID 17024120, 2006). "Patients were classified into two groups according to whether their tumours exhibited a ‘high’ or ‘low’ level of CD8+ or CD4+ lymphocyte infiltration." (PMID 16421594, 2006).
tumor (continued). "However, there was an inverse relationship between percentage tumour CD4+ T-lymphocytes and C-reactive protein (P<0.01)." (PMID 15700032, 2005). "Similarly, antigen-specific CD4+ CD25+ regulatory T cells also suppress tumor-specific CD8 T cell cytotoxicity although this mechanism relies on TGF-β secretion by regulatory cells." (PMID 16045800, 2005). "Apart from their role in expanding CD8+ T-cells, CD4+ T-cells are also involved in the activation of CD8+ independent tumoricidal mechanisms which may play a role in the eradication of tumor cells that have lost MHC class I expression." (PMID 16164749, 2005). "Furthermore, both a low tumour CD4+ T-lymphocyte infiltration and an elevated C-reactive protein predict poor cancer-specific survival." (PMID 15700032, 2005). "Indeed, addition of tumor-reactive CD4+ cells to tumor digest increases the reactivity of the CD8+ cells." (PMID 15566571, 2004). "Similarly, CD4+ T cells cultured in the presence of IL-7 plus IL-23 had 11% IFN-γ positive cells in response to MCA205 tumor with minimal spontaneous production and minimal response to MCA207 tumor digest." (PMID 15566571, 2004). "These experiments demonstrate that T cells, sensitized to tumor antigens in vivo, can be activated in vitro under conditions that promote hyperexpansion of either the CD4+ or CD8+ subset while retaining their potent therapeutic efficacy against established tumors." (PMID 15566571, 2004). "The s.c. tumor model is highly dependent on the presence of tumor-specific CD4+ T cells." (PMID 15566571, 2004). "The in vitro assay of IFN-γ production may not be fully reflective of the in vivo capacity of T cells to mediate tumor regression because CD4+ T cells cultured with IL-2 plus IL-7 had only 2% IFN-γ positive cells despite equivalent in vivo anti-tumor efficacy." (PMID 15566571, 2004). "However, depletion of both T cell subsets completely abrogated the immunogenicity of N2A-IL-2+IL-12 cells, suggesting a tumour rejection mechanism involving CD8+ T-cell activation by CD4+ T cells." (PMID 12771934, 2003). "The CD4+ Th1 killer lymphocytes, which may recognise tumour antigens differently from CD8+ cytotoxic T lymphocytes or NK cells, may be a promising candidate for the effector cells of cancer immunotherapy that targets the heterogenous clinical tumours." (PMID 14612896, 2003). "Interestingly, the kinetics of tumour formation by N2A-IL-2+IL-12 cells in CD4+- and CD8+-depleted mice showed a slight time delay compared to those of N2A-vector cells, suggesting that depletion is incomplete or that NK cells are active." (PMID 12771934, 2003). "Notably, it was observed that the CD4+ OK/IL-2AK cells expressed cytotoxic activity against autologous tumour cells and acquired Fas-L expression." (PMID 14612896, 2003). "MHC II-expressing tumour cells in tumours may thus be poor APC or even immunologically inert to CD4+ cells." (PMID 12569387, 2003). "It is hypothesised that the transfected tumour cells act as direct APC to CD4+ cells, presenting endogenous tumour antigens." (PMID 12569387, 2003). "It is of interest whether or not TCR and HLA molecules are involved in the cytotoxic mechanism of the autologous tumour-reactive CD4+ Th1 killer lymphocytes induced with OK-432 plus IL-2." (PMID 14612896, 2003). "The abnormal peptides produced by MSI-H tumours may be presented to CD4+ T-cells by the HLA-DR molecules expressed on the cell surface." (PMID 12232760, 2002). "Cytokines produced by CD4(+) T cells activate eosinophils and macrophages and these may be responsible for direct tumour cell destruction." (PMID 11875724, 2002). "CD4+ T lymphocytes are known to play pivotal roles in anti-tumour responses." (PMID 12177805, 2002). "Qualitative differences in the MHC class II antigen processing and presentation pathway may be instrumental in shaping the CD4+ T cell response directed against tumour cells." (PMID 11027433, 2000).